IGF1 (insulin like growth factor 1)
Diseases named in the same sentence as IGF1 in open-access papers (continued):
Sharing a sentence is not in itself a finding about the gene and the disease.
proliferative diabetic retinopathy (9 papers, 2011 to 2025). Advanced retinopathy due to diabetes mellitus characterized by the formation of new vessels in the retina. "IGF-1 is also known to be proangiogenic in eye pathologies associated with angiogenesis such as proliferative diabetic retinopathy (PDR) and wet age-related macular degeneration (AMD)." (PMID 35356301, 2022). "Levels of IGF-1 have been reported to be increased in the serum and vitreous of patients with proliferative diabetic retinopathy." (PMID 35054437, 2021). "In addition, there is a large amount of data indicating that an increase in IGF-1 activity may contribute to retinal neovascularization, which is a characteristic sign of proliferative diabetic retinopathy." (PMID 35248150, 2022). "IGF-1 modulates the function of retinal endothelial precursor cells, drives retinal angiogenesis in response to hypoxia, and may play a role in the pathogenesis of proliferative diabetic retinopathy." (PMID 35248150, 2022). "Meanwhile, Müller cells are activated by increased vitreous levels of HIF-1α and insulin-like growth factor 1 (IGF-1), and their activation stimulates the elevation of VEGF and basic fibroblast growth factor, which in turn promotes advancement of proliferative diabetic retinopathy." (PMID 41155177, 2025). "Therefore, the present study focused on the assessment of mRNA levels of IGF1, IGF1R, and IGFBP3 both in ERMs and PBMCs from patients with proliferative diabetic retinopathy." (PMID 24379526, 2013).
secondary hyperparathyroidism (9 papers, 2014 to 2024). Overproduction of parathyroid hormone in response to influence external to the parathyroid glands. "As expected, the two-week dietary calcium depletion led to hypocalcemia, secondary hyperparathyroidism, and increases in bone resorption and bone loss in both Igf1 osteocyte conditional knockout (cKO) mutants and WT control mice." (PMID 25635763, 2015). "This conclusion was based on two key findings: First, two weeks of dietary calcium restriction induced hypocalcemia and the associated secondary hyperparathyroidism to similar levels in both osteocyte Igf1 cKO mutant mice and age- and gender-matched WT control mice." (PMID 25635763, 2015). "Althoughthe mechanisms involved in bone loss after RYGB remain unclear, they may involve acombination of factors including secondary hyperparathyroidism and decreased levelsof insulin and IGF1." (PMID 34878062, 2021). "Morbidly obese women may have low Vitamin D, secondary hyperparathyroidism, high bone resorption, decreased GH/IGF-1, and high proinflammatory adipocytokines as the key molecular factors responsible for low BMD in these individuals." (PMID 34842748, 2021).
acute respiratory distress syndrome (8 papers, 2012 to 2023). Progressive and life-threatening pulmonary distress in the absence of an underlying pulmonary condition, usually following major trauma or surgery. "The lower circulating levels of IGF1 and IGFBP3 were also associated with the incidence and mortality of adult respiratory distress syndrome (ARDS)." (PMID 35958562, 2022). "Interestingly, immunostaining for IGF1 and its receptor in lung tissue from individuals with acute respiratory distress syndrome showed increased expression of IGF1 and IGF1R." (PMID 25790853, 2015). "Several studies demonstrate a mechanistic role for IGF1 in acute and chronic lung diseases, including acute respiratory distress syndrome (ARDS) with an upregulation of IGF1 and IGF1-R expression, but also inflammatory as well as fibrotic conditions." (PMID 34831169, 2021).
adrenocortical carcinoma (8 papers, 2012 to 2024). "In this study, by employing adrenocortical carcinoma H295R cells, we examined the interaction between Ang II and insulin/IGF-1 in ERK and AKT signaling pathways and expression of steroidogenic enzymes in the cells." (PMID 27293433, 2016). "Ang II, insulin, and insulin-like growth factor 1 (IGF-1) were shown to play important roles in adrenocortical cells, and overexpression of IGF-1 receptor was found to be associated with the development of adrenocortical carcinoma." (PMID 27293433, 2016). "Several studies have shown the involvement of IGF1/IGF1R and mTOR pathways in the pathogenesis of adrenocortical carcinoma." (PMID 29507530, 2018). "For example, IGF-1 protein expression has not been detected in the serum of patients with adrenocortical carcinoma, and IGF-1 mRNA levels are weak or absent in oesophageal squamous cell carcinoma cell lines." (PMID 28143425, 2017).
age-related macular degeneration (8 papers, 2019 to 2025). Age-related loss of vision in the central portion of the retina (macula), secondary to retinal degeneration. "Contrastingly, in neovascular age-related macular degeneration (AMD), there is an overexpression of both IGF-1 and IGF-1R in RPE." (PMID 38300646, 2024). "IGF-1 is produced in the retinal pigment epithelium (RPE), and in age-related macular degeneration (AMD), there is an increased expression of IGF-1R." (PMID 38300646, 2024). "Platelets produce platelet-derived GF (PDGF), IGF-1, TGFβ, VEGF, bFGF, EGF, platelet-derived angiogenesis factor (PDAF), and thrombospondin (TSP), and several authors have used them in eye diseases such as glaucoma, age-related macular degeneration (AMD), and RP." (PMID 33066211, 2020).
arthropathy (8 papers, 2012 to 2024). Any disorder of the joints. "The pathogenesis of arthropathy is complex, including both GH/IGF-1 excess and secondary degenerative changes." (PMID 23008710, 2012). "However, in the blood of boys with untreated arthropathy, the level of IGF-1 was significantly (p = 0.0043) lower than in healthy boys." (PMID 39766233, 2024). "In this phase arthropathy may be inverted by control of GH and IGF-1 hypersecretion." (PMID 23008710, 2012).
Ascites (8 papers, 2013 to 2025). Accumulation of fluid in the peritoneal cavity (between the layers of the peritoneum that lines the abdomen). "Levels of IGF-1 and IGF-2 in serum and ascites were all associated with mortality in univariable analyses." (PMID 38396692, 2024). "STC2 was significantly associated with levels of IGF-1 in serum and with PAPP-A in both serum and ascites." (PMID 38396692, 2024). "In the current study, we validate the value of incorporating plasma IGF-1 level instead of encephalopathy and ascites as parameters of the CTP score to create a new scoring system, Kaseb-Morris IGF-CTP system." (PMID 26098859, 2015). "However, a meaningful relation was found among IGF-1 and ascites and splenomegaly; patients with splenomegaly and ascites formed a greater proportion of patients with abnormal results of IGF-1 test." (PMID 23599716, 2013). "The study further evaluated the IGF1-CTP classification, which replaces subjective clinical assessments like ascites and encephalopathy with objective IGF-1 serum levels to potentially enhance prognostic accuracy." (PMID 39624154, 2025). "In this study in an Egyptian population, we have validated the plasma level of IGF-1 as a surrogate marker for functional liver reserve and the value of its integration into the CTP scoring system in place of encephalopathy and ascites." (PMID 26098859, 2015). "However, replacing the two subjective variables encephalopathy and ascites with IGF-1 did not lead to more precise predictions compared to the original CTP classification in a cohort of European HCC patients." (PMID 30064393, 2018).
chronic obstructive pulmonary disease (8 papers, 2009 to 2024). A chronic and progressive lung disorder characterized by the loss of elasticity of the bronchial tree and the air sacs, destruction of the air sacs wall, thickening of the bronchial wall, and mucous accumulation in the bronchial tree. "The serum IGF-1 level is decreased in chronic obstructive pulmonary disease patients in association with the severity of the disease." (PMID 32793225, 2020). "This PDE4 inhibitor is typically used in the treatment of chronic obstructive pulmonary disease (COPD) and in this case acts by the indirect inhibition of PTP1B, with the effects mediated by the crosstalk between the CREB/BDNF/TrkB and SIRT1/PTP1B/IGF1 signaling pathways." (PMID 39000142, 2024).
cognitive disorder (8 papers, 2014 to 2024). A disease affects cognitive processes. "This study is similar to our results, indicating that IGF-1 rs972936 is a key factor in inducing mental and cognitive diseases, but the risk allele is found to be the opposite of our research." (PMID 35498133, 2022).
colorectal adenoma (8 papers, 2008 to 2024). An adenoma that arises from the colon or rectum. "Our serum IGF-1 result is consistent with several studies that showed that higher IGF-1 level was significantly associated with increased risk of colorectal adenoma." (PMID 29593647, 2018). "In conclusion, we demonstrated that circulating levels of adiponectin, TNF-α, and IGF-1 were associated with colorectal adenoma risk and as such might be good biomarkers for colorectal adenoma risk in African Americans." (PMID 29593647, 2018). "Our results showed that APC, CTNNB1, IGF1, and KLF5 were frequently mutated in normal-colorectal adenoma." (PMID 31336886, 2019). "Studies have found that TG can not only activate insulin-like growth factor-1 and regulate the activity of K-ras protein, but also stimulate the abnormal proliferation of intestinal epithelial cells and promote the transformation of colorectal adenoma into tumor." (PMID 39252808, 2024). "Similarly, the AUC with 95% confidence intervals to assess the sensitivity and specificity of the biomarkers for colorectal adenoma diagnosis corresponded to 0.75 (0.70–0.80), 0.71 (0.66–0.77), and 0.64 (0.59–0.70) for adiponectin, IGF-1, and TNF-α, respectively." (PMID 29593647, 2018). "The potential role of adiponectin, leptin, IGF-1, and tumor necrosis factor alpha (TNF-α) as biomarkers in colorectal adenoma is not clear." (PMID 29593647, 2018).
Cushing syndrome (8 papers, 2008 to 2026). Cushing's syndrome (CS) encompasses a group of hormonal disorders caused by prolonged and high exposure levels to glucocorticoids that can be of either endogenous (adrenal cortex production) or exogenous (iatrogenic) origin. "Mares presenting Cushing’s syndrome obtained the highest (p < 0.0001) IGF-1 and glucose insulin ratio." (PMID 40901060, 2025). "We therefore find it unlikely that the tumor co-secreted GH, and it should be noted that elevated serum IGF1 levels have previously been reported in Cushing's syndrome (CS)." (PMID 25614825, 2015). "The pathophysiology of growth impairment in MS may include insufficient glucose uptake for adequate tissue energy, decreased circulating insulin-like growth factor 1 (IGF-1), growth hormone resistance, and hyperadrenocorticism." (PMID 41560719, 2026). "In patients with Cushing's syndrome, IGF-1 has also been found to be elevated." (PMID 18986531, 2008).
diabetic cardiomyopathy (8 papers, 2017 to 2025). Diabetic cardiomyopathy is a disorder of the heart muscle in people with diabetes. "Studies have shown that IGF-1 can effectively improve diabetic cardiomyopathy through its antioxidant and anti-inflammatory effects, as well as by activating the Akt/GSK-3β signaling pathway." (PMID 40161384, 2025). "IGF-1/IGF-1R axis has been proposed as a therapeutic candidate against the pathophysiological progress of diabetic cardiomyopathy (DCM)." (PMID 37851320, 2023). "Additionally, reduced HSP60 suppresses the IGF-1 signaling pathway, resulting in diabetic cardiomyopathy." (PMID 35845054, 2022). "Thus, B12 is a promising option for preventing diabetic cardiomyopathy via ROS reduction and IGF-1 retrieval through DNMT-SOCS1/3 signaling." (PMID 34163008, 2021). "B12 prevents and reverses the development of diabetic cardiomyopathy in the ELMO1 hypermorphic Akita mice, at least via direct scavenging of superoxide and the retrieval of IGF-1 signaling via modulating the SAMe-DNMT-SOCS1/3 cascade." (PMID 34163008, 2021).
Encephalopathy (8 papers, 2015 to 2025). Encephalopathy is a term that means brain disease, damage, or malfunction. "Our results indicate that specific patterns of CPC mobilization, in conjunction with the levels of EPO, IGF-1, and SDF-1, are strongly associated with the severity of encephalopathy and may offer valuable information regarding pathophysiological pathways and outcome." (PMID 40149963, 2025). "In contrast, IGF-1 levels showed a more complex pattern, with slightly lower levels in neonates with moderate and severe encephalopathy but gradual increases over time in all groups (hypothesis A), a pattern that was also observed earlier in preterms with encephalopathy." (PMID 40149963, 2025).
gastrointestinal stromal tumor (8 papers, 2013 to 2025). "Similarly, higher cell expression of IGF1 was found in patients with gastrointestinal stromal tumors (GIST)." (PMID 31565100, 2019).
growth hormone insensitivity syndrome (8 papers, 2007 to 2024). Growth hormone insensitivity syndrome (GHIS) is a group of diseases characterized by marked short stature associated with normal or elevated growth hormone (GH) concentrations, which fail to respond to exogenous GH administration. "Growth hormone insensitivity syndrome (GHIS) represents a group of rare genetic disorders characterised by postnatal growth failure due to functional insulin-like growth factor (IGF)-1 deficiency despite normal or elevated serum GH." (PMID 36995466, 2023). "Patients diagnosed with growth hormone insensitivity syndrome (GHIS) share common clinical characteristics of impaired postnatal growth due to low or undetectable serum IGF1 concentrations despite normal or elevated growth hormone (GH) concentrations." (PMID 29844444, 2018). "Growth hormone insensitivity syndrome (GHIS), marked by a lack of responsiveness to growth hormone (GH), presents with stunted growth after birth and significantly reduced levels of insulin-like growth factor 1 (IGF-I) in the bloodstream, despite the body producing higher amounts of GH." (PMID 39027791, 2024).
Hepatitis (8 papers, 2014 to 2026). Inflammation of the liver. "Moreover, CUMS significantly disturbed amino acid metabolism, particularly lowered the concentration of L-Aspartic Acid, reduced the expressions of GHR/IGF-1 pathway in the liver, induced liver inflammation." (PMID 42222280, 2026). "IGF1 synthesis decreases when hepatitis or liver necrosis occurs." (PMID 35196258, 2022).
hepatoblastoma (8 papers, 2000 to 2026). Hepatoblastoma (HB) is a malignant hepatic tumor and is the most common pediatric liver cancer. "In addition, it was reported that azathioprine induces resistance in hepatoblastoma cells to IGF-1, which leads to autophagy activation." (PMID 31700061, 2019). "In addition, in vitro studies have demonstrated an inhibitory effect of insulin and insulin-like growth factor-1 on CBG mRNA expression in a human hepatoblastoma derived Hep G2 cell-line." (PMID 21750736, 2011). "In addition, GH and IGF1 appear to increase the activity of CYP27A1, a multifunctional cytochrome P450 enzyme which, among its complex functions, catalyses the 25 hydroxylation of vitamin D in hepatoblastoma cells." (PMID 39149044, 2024).
hip fracture (8 papers, 2014 to 2025). Traumatic or pathological injury to the hip in which the continuity of either the femoral head, femoral neck, intertrochanteric or subtrochanteric regions is broken. "Previously published studies have suggested lower circulating vitamin D and IGF-1 levels in vegetarians than in meat-eaters, and inverse associations of these biomarkers with hip fracture risk through their effects on bone and muscle health." (PMID 37501206, 2023). "Moreover, in men, IGF-1 levels were positively correlated with BMD at the femoral neck and total hip, and negatively linked with the 10-year probability of major osteoporotic fractures (MOFs) and hip fractures (HFs)." (PMID 39741509, 2024). "Meta-analyses and umbrella reviews support a protective role of protein above the RDA for hip fracture and BMD maintenance in older adults, likely mediated through preservation of lean mass, stimulation of IGF-1, and improved muscle–bone mechanical coupling." (PMID 41470790, 2025).
Hyperammonemia (8 papers, 2022 to 2024). An increased concentration of ammonia in the blood. "Taken together, LC can reduce the myostatin level through direct pathways like activating the IGF‐1 pathway or decreasing hyperammonemia." (PMID 37078370, 2023). "Consumption of alcohol may result in dysbiosis and autophagy of the gut microbiota-induced hyperammonemia, which initiates the up-regulation of muscle protein breakdown and the down-regulation of muscle protein synthesis by activating myostatin, AMPK, and REDD1, and deactivating IGF-1." (PMID 38001472, 2023).
Hypoalbuminemia (8 papers, 2019 to 2025). The concentration of albumin in the blood circulation is below the lower limit of normal. "Reports with association between hypoalbuminemia and growth hormone (GH) or insulin-like growth factor-1 (IGF-1) were also scant." (PMID 33607942, 2021). "A study of hemodialysis patients revealed that hypoalbuminemia was significantly associated with lower IGF-1." (PMID 33607942, 2021). "Moreover, hypoalbuminemia causes a decrease in insulin-like growth factor-1 synthesis, thereby leading to a decreased number of osteoblasts, decreased cellular activity, increased osteoclast lifespan, increased bone resorption, and decreased bone remodeling." (PMID 36494810, 2022). "Regarding nutritional markers, patients with low skeletal muscle and adipose mass had a higher incidence of hypoalbuminemia (p < 0.001), lower prealbumin (p < 0.001), and lower IGF-1 levels (p = 0.031)." (PMID 37242125, 2023). "Furthermore, hypoalbuminemia can lead to reduced synthesis of insulin-like growth factor-1, thereby affecting factors such as the quantity and activity of osteoblasts and bone remodeling." (PMID 39655346, 2024). "In addition, patients with low skeletal muscle and adipose mass had a higher incidence of hypoalbuminemia and low IGF-1 levels." (PMID 37242125, 2023). "Interestingly, hepatic IGF-1 synthesis is thyroid hormone-dependent, and hypoalbuminemia may further impair fluid homeostasis, linking hepatic function to orbital pathology." (PMID 40978853, 2025). "Body composition does not affect post-surgery complications.BCS2 group worse preoperative markers (hypoalbuminemia, lower prealbumin and IGF-1).BCS2 group progressively shorter OS.NAT was not the 3y OS independent prognostic factor after radical gastrectomy." (PMID 37242125, 2023).
insulinoma (8 papers, 2015 to 2025). "The process of tumour detection involved biochemical screening tests including gastrin, glucose, insulin, chromogranin-A, pancreatic polypeptide, glucagon, vasointestinal polypeptide, prolactin and IGF-1 to assess for gastrinoma, insulinoma, enteropancreatic and anterior pituitary tumours." (PMID 31797261, 2020).
iron deficiency (8 papers, 2013 to 2025). "Since magnesium status seems to be strictly related to muscle ATP and IGF-1 levels, it becomes important to check whether the contemporary presence of both magnesium deficiency and low IGF-1 levels can be related to age-related phenomena." (PMID 24152751, 2013). "Magnesium deficiency might exacerbate the age-related decline in IGF-1 levels, playing an additive negative effect in impairing physical performance." (PMID 24152751, 2013).